TNF (tumor necrosis factor)
Diseases named in the same sentence as TNF in open-access papers (continued):
Sharing a sentence is not in itself a finding about the gene and the disease.
influenza (continued). "It is also possible that the efficacy of annual influenza vaccination in anti-TNF treated patients could be improved by timing immunization with the decline in biological effect of the corresponding agent." (PMID 22177419, 2011). "Moreover, the influenza-specific memory B cell frequencies continued to decrease disproportionally at six months in anti-TNF treated patients as compared with all other groups." (PMID 22177419, 2011). "Moreover, our results indicate that every effort should be made to provide annual influenza immunization and indicated vaccination updates to RA patients before anti-TNF therapy is initiated." (PMID 22177419, 2011). "We therefore asked if this effector response to influenza vaccination is also impacted by anti-TNF." (PMID 22177419, 2011). "Therefore, the serum antibody response against multiple components of seasonal influenza vaccine is impaired in RA patients treated with anti-TNF." (PMID 22177419, 2011). "As the influenza vaccine response is largely a secondary immune response, TNF blockade may be compromising the memory B cell response, perhaps by altering their maintenance or responsiveness." (PMID 22177419, 2011). "While Aldridge and colleagues argue that PPAR-gamma agonists exert their effects during an influenza infection by down-regulating the recruitment of TNF-α/i-NOS producing dendritic cells from the bone marrow, we did not observe any changes in this cell population." (PMID 20967263, 2010). "As a result, all these TNF-α activated mediators could contribute to the infiltration of inflammatory cells into the influenza infected respiratory tract." (PMID 21108843, 2010). "To further investigate the effect of rm-APC treatment on the inflammatory response in severe influenza, we determined pulmonary levels of various cytokines (TNF-α, IL-1β, IL-6, IL-10, IL-12p70, IFN-γ) and chemokines (KC, MIP-2) in lung homogenates obtained 48 and 96 hours after infection." (PMID 20398279, 2010). "In response to influenza viral entry, epithelial and immune cells induce pro-inflammatory cytokines and chemokines such as interleukin-1β, interleukin-6, tumor necrosis factor α (TNFα), CCL2, CCL3, and CCL5, which recruit macrophages and neutrophils to the site of infection to control the virus." (PMID 39846844, 2025). "Additionally, after influenza vaccination, increases in IL-6 and TNF-α are observed." (PMID 40718526, 2025). "Furthermore, IL-10–producing neutrophils in cattle modulate inflammation during parasitic infections and may similarly attenuate IFN-γ- and TNF-α-mediated lung pathology during influenza infection." (PMID 40872830, 2025). "Influenza infection triggers an intense systemic inflammatory response characterized by the release of pro-inflammatory cytokines such as interleukins (IL-1, IL-6, IL-8), tumor necrosis factor-alpha, and interferons, which activate inflammatory cells within atherosclerotic plaques." (PMID 40499619, 2025). "While the antiviral protective mechanism of IRF7 in the immune response is well defined, there is evidence suggesting that MX1 may exert its anti-influenza protective effect by downregulating factors such as IL-6, IL-1β and TNFα, among others, involved in excessive cytokine response." (PMID 38932312, 2024). "Moreover, stimulation with the influenza vaccine or CpG resulted in increased IL-6 levels in the culture supernatants, suggesting innate cell activation as well as IFNγ and TNF which may indicate Th1 helper responses." (PMID 39355250, 2024). "Interestingly, influenza decreased the levels of TNF-α in the serum." (PMID 37630849, 2023). "In the context of influenza, LANCL2‐deficient mice have higher levels of IL‐6 and MCP‐1 in their lungs, while the oral treatment of infected mice with selective LANCL2 ligands abscisic acid and NSC61610 reduced the levels of TNF and MCP‐1 in the lung during IAV infection." (PMID 36969366, 2023).
influenza (continued). "HCMV-seropositivity, as well as inflamm-ageing, also cause the increase in both serum TNF-α and TNF-α-producing B cells, negatively correlated in vitro with the ability to respond to stimulation, measured by AID, and, in vivo, with serum response to the influenza vaccine." (PMID 36077216, 2022). "However, levels of influenza-specific TNF-α were significantly increased in the LAIV/S." (PMID 33497364, 2021). "Interestingly, it has been observed that, despite elevated TNFα in Type 2 diabetes patients, the expected inflammation-associated drop in influenza vaccine response does not occur in old or young subjects." (PMID 36845567, 2021). "Moreover, splenic unstimulated B cells from P2KO mice make higher levels of TNF-α and IL-6 mRNA than those from WT mice and these negatively correlate with B cell function, measured in vivo by the response to the influenza vaccine and in vitro by AID mRNA expression in stimulated B cell cultures." (PMID 32180773, 2020). "Furthermore, it has been hypothesized that influenza stimulates TNF-α gene transcription activators or may interfere with labile transcription repressor proteins and stabilizes TNF-α mRNA by delaying its degradation." (PMID 29978355, 2018). "In an influenza model, direct comparison of the two sexes reveals that female mice exhibit greater morbidity and mortality than male mice, potentially because of elevated levels of cytokines, such as tumor necrosis factor (TNF)-α and C-C motif chemokine ligand 2 (CCL2), in female mice." (PMID 29284060, 2017). "Therefore, the increase in CCL-2, TNF-α and GM-CSF in our study may explain the observed increase in macrophages and neutrophils following CS and influenza infection." (PMID 26877172, 2016). "Methotrexate, rituximab and abatacept are associated with decreased immunogenicity to both influenza and pneumococcal vaccination, however TNF inhibitors, tocilizumab and sulfasalazine do not appear to have a negative effect on vaccine immunogenicity (albeit limited data for the latter two)." (PMID 27491386, 2016). "Moreover, we found previously that dietary RGs given for 14 days prior to influenza virus infection reduced influenza-induced symptoms by acting on dendritic cells (tipDCs) producing tumor necrosis factor alpha (TNF-α)/inducible nitric oxide synthase (iNOS) in the lungs." (PMID 24392148, 2014). "Importantly, peptides enriched for non-cross-reactive A/California/04/09 specificities induced a higher proportion of Thpp-like IFNγ−IL-2+TNFα+ CD4 T cells than peptide pools cross-reactive with previous influenza strains, which induced more Th1 (IFNγ+TNFα+) responses." (PMID 23526940, 2013). "Thus, CD8+ T cells can indirectly mediate immunopathology in a transgenic mouse model of influenza infection by producing TNF-α upon specific antigen recognition that results in alveolar epithelial cell chemokine production and the subsequent cellular infiltration and lung injury." (PMID 24223177, 2013). "Importantly however, TNF-α has been shown to play a role in protection against secondary bacterial pneumonia after influenza infection and anti-TNF-α therapies, which target both tmTNF-α and sTNF-α, have been associated with an increased risk for bacterial infection." (PMID 24223177, 2013). "However, the role of TNF-α in virus clearance and immunopathologic lung injuries during influenza virus infection is still controversial, and whether direct inhibition of TNF-α can elicit protection from influenza infection is still unknown." (PMID 24373231, 2013). "As different influenza vaccine strategies are pursued, including adjuvanted vaccines and a pan-influenza vaccine, it may be important to maintain a balance between effectors and the IFNγ−IL-2+TNFα+ producing cells, similar to that observed with tetanus toxoid and other protective protein vaccines." (PMID 23526940, 2013).
influenza (continued). "CD8+ T-cell-specific inhibition of ADAM17-mediated processing of TNF-α resulted in decreased chemokine production by alveolar epithelial cells and reduced cellular infiltration of the airways, attenuating tissue injury and mortality in a transgenic mouse model of influenza pneumonia." (PMID 24223177, 2013). "However, it is interesting that the four pro-inflammatory cytokines induced by Pam2-ODN 4 h after treatment (IL-1α, IL-1β, IL-6, and TNF) are also the first four pro-inflammatory cytokines induced from respiratory epithelial cells in native influenza infections." (PMID 22299046, 2012). "The enhanced induction of both IFNγ and TNF by Fluzone adjuvanted with GLA-SE could positively impact an influenza vaccination program aimed at the elderly population since prior studies have reported a putative correlation of cell mediated immunity and protection against influenza." (PMID 21060869, 2010). "Since influenza H5N1 virus is reportedly resistant to the anti-viral effects of interferons and TNF-α and can lead to delayed apoptosis of infected macrophages, the clearance of the virus and lung inflammation would take a longer period of time than with seasonal influenza infection." (PMID 19874627, 2009). "Network pharmacology identified genistein and daidzein as key bioactive constituents targeting hub proteins TNF, AKT1, EGFR, SRC, and MMP9, which mediate pathological process in influenza." (PMID 41957261, 2026). "A significant correlation was evidenced between TNF-α protein and mRNA expression and the glycolysis rate-limiting enzyme PFK following influenza infection of monocytes." (PMID 41511331, 2025). "Positive or negative statistical correlations have been reported between PFK1 and specific immune mediators, such as TNFα, TLR3 and TLR7 at the protein or gene level in cultured monocytes upon influenza infection." (PMID 41511331, 2025). "Mice vaccinated with BPZE1 as infants showed reduced production of the four pro-inflammatory cytokines TNF, IL-6, IL-1β, and IFN-γ in response to influenza infection compared to unvaccinated animals." (PMID 40612502, 2025). "For instance, proinflammatory cytokines like TNF-α and macrophage migration inhibitory factor (MIF) are elevated on the day after influenza vaccination, correlating with these minor symptoms." (PMID 40640868, 2025). "In the Influenza infection group, the Spring PM exposure induced elevated expression of IFN-γ, IL-1β, IL-6, IL-8, TNF-α, IL-10, MCP-1, and GM-CSF relative to the control exposure." (PMID 40671793, 2025). "We therefore measured the levels of several cytokines, including the pro-inflammatory TNF, IL-1β, IL-6, and IFN-γ, as well as IL-4, IL-10, IL-17A, and IL-22, in BAL samples from mice 5 days after influenza challenge." (PMID 40612502, 2025). "IL‐6 KO mice have a similar inflammatory cytokine profile to WT mice during post‐influenza MRSA pneumonia, including GM‐CSF, RANTES, TNFα, IFNγ, and IL‐4." (PMID 39921246, 2025). "Upon re-exposure to influenza antigens, these memory subsets promptly recognize viral peptides presented by local APCs and produce cytokines such as IFN-γ, TNF-α, and IL-2 within hours." (PMID 40872830, 2025). "While essential for viral clearance, TNF-α overproduction can lead to excessive inflammation, contributing to conditions like ARDS during severe influenza infections." (PMID 39456722, 2024). "The number of influenza-specific CD4+ polypositive T cells, defined as CD4+ T cells producing at least two of the following immune markers: CD40L, IFNγ, IL-2, and TNFα, exhibited similar trends between cohorts at any visit for any vaccine strain." (PMID 39340066, 2024). "Influenza-infection-induced Th1 effector cells express antiviral cytokines, such as IFN-γ, TNFα, and IL-2, and activate alveolar macrophages." (PMID 39066362, 2024). "Network pharmacology studies also suggested that the anti-influenza effect of HQS was related to TLRs, MAPK, TNF, and other signaling pathways." (PMID 36739385, 2023).
influenza (continued). "Signaling pathways, such as TNF and CCL, were found to be involved at D7 and D14 after influenza infection." (PMID 37415817, 2023). "Six core targets of HQS against influenza were screened by this approach, and the main pathways included the MAPK-related signaling pathway, TNF signaling pathway, TLR signaling pathway, etc." (PMID 36739385, 2023). "At 7 dpi with influenza, BAL from mice exposed to e-cigarette aerosol generated from the carrier VG/PG or from VG/PG/Nic had significantly higher levels of IFN-γ, TNFα, IL-1β, IL-6, IL-17A, and MCP-1 compared to mice exposed to air." (PMID 36999019, 2023). "In mice with influenza infection, medicinal inhibition of COX2 by celecoxib reduces TNF-α, granulocyte colony-stimulating factor, and IL-6 levels in bronchoalveolar lavage fluid without a substantial increase in viral titers." (PMID 36671699, 2022). "The analysis using CytoHubba, TNF, IL10, IL-6, IL-1B, JUN, and MAPK1 was found to have the highest average scores and identified as crucial targets for the anti-influenza efficacy of TFA." (PMID 35123452, 2022). "Previous research has shown that inflammation-related factors (IL-1, TNF, CXCL1, CXCL2, S100A8, and S100A9) predominantly express in neutrophils, and neutrophils infiltration largely account for lethal influenza infection." (PMID 35495713, 2022). "With the merger of PPI network, we have identified a core network, including TNF, IL-6, IL-1B, JUN, and MAPK1, as crucial targets of the anti-influenza efficacy of TFA." (PMID 35123452, 2022). "Proinflammatory cytokines interleukin 1β (IL-1β) and tumor necrosis factor-α (TNF-α) that are strongly expressed in the vascular niche in response to injury suppressed COUP-TF2 expression, while COUP-TF2 ablation exacerbated influenza lung injury." (PMID 36601582, 2022). "QFYD also downregulated inflammatory signaling pathways, including MAPK, TNFα, and JAK-STAT signaling pathways, which are important inflammatory signaling pathways and targets in the progression of influenza." (PMID 35677448, 2022). "Other studies have described impaired influenza and pneumococcal vaccination in IBD patients receiving therapy with anti-TNF." (PMID 35629116, 2022). "The core network, including the pro-inflammatory TNFα, IL-6, IL-1β, MAPK, and RIG-I receptor signaling pathways, is further confirmed as the critical target of TFA anti-influenza efficacy." (PMID 35123452, 2022). "One of the affected cytokines in influenza infection is TNF-α and it has been shown that the expression of TNF-α is induced." (PMID 35606770, 2022). "A core network containing the pro-inflammatory TNFα, IL-6, IL-1β, MAPKs, and RIG-I receptor signaling pathway was further confirmed as the crucial targets for anti-influenza efficacy of TFA." (PMID 35123452, 2022). "Still, some patients were able to mount a good humoral response to inactivated influenza vaccination despite DMARD and/or anti-TNF therapy." (PMID 34136315, 2021). "Azithromycin and other macrolides, like bafilomycin A1, erythromycin, and clarithromycin were found to impede the making of IL-1β, IL-6, IL-8, TNF-α, and ICAM-1 in influenza- and RV-modeled infections." (PMID 33937285, 2021). "Levels of IL-6, IL-8, TNF-α, and CCL3 were also increased in our cohort of pandemic influenza A(H1N1) patients, validating our previous observations." (PMID 33995342, 2021). "In contrast, levels of IL-1RA, IL-2, TNF-α, CCL3, and G-CSF were more increased among pandemic influenza A(H1N1) patients." (PMID 33995342, 2021). "The higher level of IgG3 production was found to be positively correlated with the level of tumor necrosis factor-α (TNF-α) and interleukin-6 (IL-6) because IL-6 is the major cytokine produced during influenza infection." (PMID 33302987, 2020). "Ox-LDL synergistically increases the expression of pro-inflammatory molecules such as IL-1β, IL-6, TNFα, and MMP-9 in response to H1N1 PDM 2009 influenza in HUVEC cells." (PMID 33193350, 2020).
influenza (continued). "RAW264.7 macrophage cells and primary murine alveolar macrophages also showed increased IL-6, TNF-α, IFN-β, and/or IL-1β production in the presence of 1-methyltryptophan another IDO pharmacological competitive inhibitor, following influenza infection." (PMID 32267860, 2020). "After influenza infection, IFN-α/β, IFN-α, and IL-2 appear to have protective roles against influenza infection, while IL-1, TNF-α, and IL-6 seem to be involved in the inflammatory phase of the infection." (PMID 33374214, 2020). "TNF-α production by NK cells and CD8+ T cells broadly activates pro-inflammatory and migratory responses which contribute to influenza infection control." (PMID 32974217, 2020). "The overlap in expression characteristics of TNF-α, IFN-γ, and IL-17 in patients with severe influenza infection is an interesting observation." (PMID 32974217, 2020). "Our findings in ANP32B+/+ and ANP32B−/− mice on the other hand suggest that ANP32B is required for the induction of a subset of pro-inflammatory cytokine responses (TNF-α, MCP-1, IL-1β, and IL-6), upon influenza infection in the murine lung." (PMID 32231671, 2020). "Serum concentration of IL-6, IL-1β, TNFα, IFNγ were found elevated in cases of HAdV, RSV, and influenza AURTIs compared to age-specific normal values." (PMID 33066100, 2020). "T-cell responses were assessed by analysing the frequencies of influenza-specific CD4+ and CD8+ T producing IFN-γ, IL-2, and TNF-α in PBMC harvested on days 1 and 22 from participants in groups MAP-FA-0, MAP-FA-15, MAP-UA-15, and IM-QIV-15." (PMID 32181756, 2020). "Levels of multiple pro-inflammatory cytokines, such as interleukins (ILs), tumor necrosis factor (TNF), interferons (IFNs), and chemokines, in the samples of patients with severe influenza, increased." (PMID 31293574, 2019). "Influenza infection of wild-type female mice resulted in activation and increased functionality of lung ILC1s as demonstrated by their enhanced production of IFN-γ and TNF-α early after infection." (PMID 29623077, 2018). "To directly address the use of TNF/CHP nanoparticles as a vaccine adjuvant on protective immunity, we employed a lethal influenza challenge mouse model." (PMID 26421290, 2015). "In summary, these data indicate that CD4+ T cells are involved in the immune response to influenza infection in pigs and that a considerable proportion of responding cells is multifunctional in terms of IFN-γ, TNF-α and IL-2 production." (PMID 25971313, 2015). "We also demonstrated that treatment with Pam2Cys promotes the development of influenza-specific adaptive immune responses that included IFN-γ, TNF-α, and IL-2 secreting CD8+ T-cells, which were found to persist in the lung up to 6 weeks after infection." (PMID 24624130, 2014). "In conclusion, our data showing the expression patterns of NLRP3, IL-1β and TNF-α in H9N2 AIV infected mice further support that NLRP3 inflammasome protein play a crucial role in the physiological and pathological processes of influenza infection." (PMID 25547136, 2014). "Reduction of influenza RNPs entry into the nucleus tolled A(H1N1)pdm09 life cycle in macrophages earlier than usual, limiting influenza's ability to induce TNF-α." (PMID 24978204, 2014). "The role of TNF and TNFAIP3 in inflammation is well known, and TNFAIP3 has been shown previously to play a specific role in influenza infection." (PMID 23935999, 2013). "In another recent study, the absence of TNF in all cells was found to result in increased inflammation, greater weight loss and increased numbers of macrophages, polymorphonuclear cells and antigen-specific T cells in the airway lumen during influenza infection, consistent with our T cell results." (PMID 23874808, 2013). "The antiinfluenza properties of IL-6, TNF-α, and IFN-γ have been discussed in many studies, despite their participation in cytokine storms triggered by influenza infection." (PMID 24159339, 2013).